BACH1 (BACH transcriptional regulator 1)
Diseases named in the same sentence as BACH1 in open-access papers (continued):
Sharing a sentence is not in itself a finding about the gene and the disease.
tumor (continued). "This potential of BACH1 to promote tumor cell invasion was further confirmed by an in vitro invasion assay demonstrating an approximately twofold increase in the invasion abilities of BACH1-overexpressing as compared with control ES2 cells." (PMID 32132179, 2020). "In contrast, BACH1 overexpression enhances intratumoral blood vessel density and peritumoral lymphatic vessel diameter in ovarian and lung mouse tumor models." (PMID 32132179, 2020). "Sustained Nrf2 activation upregulates home oxygenase-1 (Ho-1) that catabolizes free heme, causing functional inactivation of ubiquitin ligase Fbxo22 and the subsequent stabilization of BACH1 and tumor cell metastasis." (PMID 32226544, 2020). "In stark contrast, xenografts carrying BACH1-depleted P-GBM2 cells displayed a significant regression of tumor growth following TMZ treatment." (PMID 28000777, 2016). "This study determined the mRNA levels of Nrf2, Keap1, Bach1, and Hmox1, both in the tumor and in normal tissues, to investigate their correlations in CRC." (PMID 27999449, 2016). "The tumor had lower Hmox1 but higher Bach1 mRNA levels and ratio with Nrf2 than the normal tissue in CRC." (PMID 27999449, 2016). "In the tumor tissue with undetectable Bach1 mRNA expression, the correlation between the mRNA levels of Keap1 and Hmox1 was the only one that remained significant." (PMID 27999449, 2016). "The tumor had higher Keap1/Nrf2 and Bach1/Nrf2 but lower Homx1/Nrf2 mRNA ratios compared to the normal tissue." (PMID 27999449, 2016). "Bach1 mRNA expressions were undetectable in some subjects (22/84) and were insignificantly correlated between the tumor and normal tissues, suggesting that the regulation of Bach1 expression is different between tissues and among subjects of CRC." (PMID 27999449, 2016). "Immunostaining was performed to evaluate the expression of JMJD1A and BACH1 in NPC tumor cells and adjacent normal nasopharyngeal epithelium." (PMID 21541331, 2011). "Black women experience larger tumors, and we found that BACH1 levels correlated with tumor size." (PMID 40710214, 2025). "We analyzed BACH1 protein levels in tumor tissues using immunohistochemistry assays." (PMID 40710214, 2025). "Consequently, focusing on controlling BACH1 regulation in the tumor microenvironment is seen as a potential method for combating tumors." (PMID 39887888, 2025). "A Kruskal–Wallis’s rank sum test rejected our omnibus hypothesis that each tumor grade had the same BACH1 expression level based on histological tumor grade." (PMID 40710214, 2025). "We tested BACH1 expression levels using IHC scores by tumor size, measured by diameter." (PMID 40710214, 2025). "Like most FBXO proteins, FBXO22 contains the F-box domain in the N-terminus and protein–protein interaction domains for substrate recognition in the C-terminus and FBXO22 has been shown to regulate tumor progression and metastasis by targeting key regulators like BACH1." (PMID 40263598, 2025). "An independent group comparison of basal-like (N = 32) and luminal A (N = 76) subtypes, which have the most abundant patient samples, indicates that BACH1 IHC scores were significantly higher in the basal-like tumor subtype (p < 0.001, Rank-Biserial Correlation = 0.517)." (PMID 40710214, 2025). "BTB domain and CNC homology 1 (BACH1), a member of the Cap ‘n’ Collar and basic region leucine zipper family of transcription factors, plays several key roles in the oxidative stress response, heme homeostasis, senescence, tumor progression, and metastasis." (PMID 40263598, 2025). "There are various factors that can influence tumor metabolism by modulating BACH1." (PMID 39887888, 2025). "In addition, it is suggested that additional analyses of MCT1 and BACH1 expression at the single-cell level in each tumor type be conducted, as we analyzed total IHC scores per tumor slide rather than examining cellular levels of each molecule." (PMID 40710214, 2025).
tumor (continued). "Furthermore, the role of the SDCBP‒BACH1 axis in tumor progression and metastasis, both in vitro and in vivo, was assessed." (PMID 40263598, 2025). "We further dissected subtypes of tumors among Black and White women to investigate whether BACH1 levels differed by tumor subtype and race." (PMID 40710214, 2025). "Notably, BACH1 was shown to regulate angiogenesis both in collaboration with and independently of HIF1α, highlighting its central role in antioxidant-induced tumor progression." (PMID 40646353, 2025). "In addition, studies have shown that Bach1 contributes to maintaining tumor microenvironment stability and inhibiting cancer progression by modulating ferroptosis." (PMID 39905004, 2025). "While further research is warranted to elucidate these mechanisms, our findings suggest that RKIP's tumor‐suppressive effects in EGFR‐mutant LUAD may be mediated through alternative pathways beyond BACH1‐EMT regulation." (PMID 40720248, 2025). "The BACH family of transcription factors is known to regulate VEGF-C expression through direct binding to its promoter, and BACH1 overexpression enhances intra-tumoral angiogenesis and the peritumoral lymphatic vessel diameter in ovarian and lung mouse tumor models." (PMID 40507333, 2025). "Yet, it is unclear whether BACH1 expression levels are differentiated by tumor characteristics or the clinical variables of patients." (PMID 40710214, 2025). "When we further analyzed their correlation in each tumor subtype, we similarly observed a positive but insignificant trend between BACH1 and MCT1 in the basal-like (0.226, p = 0.222; N = 31), luminal A (0.237, p = 0.048; N = 70), and luminal B (0.353, p = 492; N = 6) subtypes." (PMID 40710214, 2025). "To further investigate whether the signature reflects BACH1 levels, we analysed the correlation between the signature and BACH1 protein abundance across a large panel of cell lines from multiple tumour types." (PMID 40716152, 2025). "The majority of studies showed that high BACH1 expression increases tumor angiogenesis." (PMID 39887888, 2025). "Furthermore, BRIP1 (also known as BACH1) is a DNA helicase which acts as a potential tumor suppressor." (PMID 40727930, 2025). "Our general hypothesis was to determine whether BACH1 levels were differentiated according to tumor characteristics." (PMID 40710214, 2025). "Next, we explored whether MCT1 levels were different or equal in terms of histological tumor grade, as we did for the BACH1 analysis." (PMID 40710214, 2025). "Inhibiting BACH1 could disrupt tumor cell metabolism, increasing their sensitivity to chemotherapy and other treatments." (PMID 39887888, 2025). "In addition, regulation of mitochondrial metabolism inhibits tumor growth by targeting BACH1, thereby sensitizing tumors to mitochondrial inhibitors." (PMID 38321558, 2024). "Notably, there is a recent study uncovering a role for NRF2 and BACH1 in promoting NSCLC tumor metastasis." (PMID 39235454, 2024). "Notably, circRNAs, lncRNAs and miRNAs act as upstream regulators of BACH1 in tumor cell proliferation." (PMID 38321558, 2024). "BACH1 is critical for tumor metastasis induced by the Keto diet." (PMID 38838145, 2024). "Hence, targeting BACH1 regulation in the TME is considered as highly promising anti-tumor therapeutic strategy." (PMID 38321558, 2024). "Inhibiting BACH1 expression sensitized tumor cells to metformin both in vitro and in vivo." (PMID 38255314, 2024). "Immunohistochemistry analysis confirmed that the tumor suppressive effect of S.C may indeed rely on activating ROS/USP47/BACH1/HMOX1 axis." (PMID 38195593, 2024). "This raises the possibility that activation of BACH1 by the Keto diet may suppress tumor growth through the down-regulation of SLC7A11 and the activation of ferroptosis." (PMID 38838145, 2024).
tumor (continued). "Therefore, TBE53 is a potentially more potent alternative to hemin for inducing BACH1 degradation in anti-tumor therapy." (PMID 38321558, 2024). "BACH1 is expected to become an effective novel target for tumor therapy." (PMID 38321558, 2024). "Intriguingly, the function of BACH1 is different during tumor formation." (PMID 38321558, 2024). "Moreover, ChIP analysis of tumor tissues revealed that the recruitment of BACH1 to the promoters of CEMIP, CXCL14, and NGFR was markedly enhanced in tumors from the Keto diet group compared to the Ctrl group." (PMID 38838145, 2024). "In addition, we pretreated both control and KYSE150-BACH1-OE cells with 1 μM RSL3 for 6 h, and the subcutaneous tumorigenesis experiment showed that the in vivo proliferation and the tumor weight of BACH1-OE cells were dramatically attenuated." (PMID 36670112, 2023). "These somewhat contradictory results suggest that the role of BACH1 in GC is complex and may be related to the tumor immune microenvironment." (PMID 37228820, 2023). "BACH1 expression level was also higher in NSCLC tissues than in non-tumor tissues (p < 0.0001)." (PMID 37946265, 2023). "BACH1 is the critical inducer in chemotactic tumor cells actively seeking refuge in the lymph." (PMID 36670112, 2023). "To investigate whether elevated anti-BACH1 serum autoantibody levels reflect increased antigen levels in ESCC tumor tissues, we performed an immunohistochemical staining assay of BACH1 using tissue microarrays." (PMID 36670112, 2023). "BACH1, a transcription factor, plays a crucial role both in tumor metastasis and tumor metabolism." (PMID 38202657, 2023). "In addition, BACH1 also functions as a tumor suppressor and controls survival of AML cells by regulating HO-1 expression, suggesting that functional upregulation of BACH1 is an alternative therapeutic strategy for antileukemic therapy." (PMID 36774506, 2023). "Moreover, enrichment analysis indicated that BACH1 was involved in the activation of certain pathways and was tightly related to tumor progression and poor prognoses." (PMID 35801241, 2022). "In contrast, knockdown of BACH1 decreased tumor growth and lung metastasis but increased OS." (PMID 35154476, 2022). "The impact of BACH1 on tumor progression and prognoses needs to be confirmed experimentally." (PMID 35801241, 2022). "In addition, BACH1 is a promising therapeutic target against tumour metastasis in various tumour types [40,43,]." (PMID 35313207, 2022). "As hemin is a potent BACH1 inhibitor, we then tested whether pharmacologic inhibition of BACH1 using hemin could elicit tumor suppression in vivo similar to shBACH1 when co-treated with an MCT1 inhibitor." (PMID 35406740, 2022). "Therefore, our results suggest that BACH1 inhibition helps increase the efficacy of MCT1 inhibitors for tumor suppression in vivo, recommending a novel combination therapy using hemin and MCT1 inhibitors." (PMID 35406740, 2022). "However, adding a BACH1 drug, hemin, produced higher efficacy for tumor suppression compared to the single treatment of both MCT1 inhibitors, both at a lower dosage or in a shorter term." (PMID 35406740, 2022). "The results of subsequent experiments indicated that BACH1 enhanced the growth of tumor xenografts." (PMID 33932125, 2021). "Subsequently, we detected the long‐term effect of BACH1 on tumor progression in vivo." (PMID 33932125, 2021). "Accumulating evidence has shown that Bach1 contributes to tumor metastasis." (PMID 34949193, 2021). "Gene ontology (GO) enrichment analysis was utilized for predicting the potential biological function of miR-494-3p, and BACH1 also partook in regulating DNA-templated, which might influence the growth of the tumor cells." (PMID 34191748, 2021). "To assess whether enhanced expression of BACH1 in tumor cells can stimulate blood and lymphatic vessel expansion during tumor progression as well as metastatic spread, we analyzed various ovarian and lung mouse tumors." (PMID 32132179, 2020).
tumor (continued). "We, thus, examined the effects of BACH1 on the lymphatic vasculature in various mouse tumor models." (PMID 32132179, 2020). "Notably, Bach1 can also function as a tumor suppressor, and at least some of its anticancer properties can likely be attributed to its role as a regulator of HO-1 expression." (PMID 30370001, 2018). "The tumor had lower Hmox1 and higher Bach1 mRNA levels than the normal tissue." (PMID 27999449, 2016). "The tumor had lower Hmox1 but higher Bach1 mRNA levels than the normal tissue." (PMID 27999449, 2016). "We examined whether BACH1 levels differed by histological tumor grade, categorized as follows: Grade 1: well-differentiated, Grade 2: moderately and intermediate differentiated, Grade 3: poorly differentiated and dedifferentiated, and ND: cell type not determined or unclassified." (PMID 40710214, 2025). "When BACH1 IHC scores were compared in the two tumor diameter groups using the Mann–Whitney U test for independent samples, we found a significant difference (p = 0.015) between the groups, showing that the bigger tumor group had higher BACH1 IHC scores than the smaller tumor group." (PMID 40710214, 2025). "Indeed, BACH1 mRNA expression is induced by hypoxia, which implies a tumor microenvironment effect." (PMID 40710214, 2025). "However, metformin suppressed the growth of BACH1-expressing BM1 or MB436 tumor xenografts." (PMID 40430851, 2025). "However, the function of SDCBP in TNBC tumor progression and in BACH1 stability remains elusive." (PMID 40263598, 2025). "In addition, we discuss the potential roles of BACH1 in drug resistance and tumor immunity." (PMID 38321558, 2024). "Our subsequent functional studies revealed that BACH1 inhibited OA biosynthesis, and the low OA content in the cell membrane and the high OA content in lymph fluid formed a concentration gradient, leading to the chemoattraction of tumor cells and metastasis via lymphatic vessels." (PMID 36670112, 2023). "Likewise, Bach1 is regulated by numerous factors in non-tumor tissues." (PMID 33809182, 2021). "Thus, BACH1 significantly enhanced tumor migration and invasion in ESCC cells." (PMID 33932125, 2021). "However, BACH1 overexpression significantly increased the density of CD31+ blood vessels in xenograft tumor tissues derived from mice subcutaneously injected with KYSE150‐BACH1 cells compared with that derived from mice injected with KYSE150‐Vector control cells." (PMID 33932125, 2021). "For example, in RAS‐driven pancreatic ductal adenocarcinoma, BACH1 directly represses the expression of the transcription factor FOXA1, which is known to activate the expression of CDH1 encoding E‐cadherin, CLDN3, and CLDN4 to induce the EMT and tumor metastasis." (PMID 33932125, 2021). "However, Bach-1 is below detectable level in many non-tumor samples." (PMID 32228546, 2020). "Heme oxygenase 1 (Hmox1) plays an important role in the growth and spread of tumor, and its expression is regulated positively by Nrf2 [nuclear factor (erythroid-derived 2)-like 2; NFE2L2] and negatively by kelch-like ECH-associated protein 1 (Keap1) and by BTB and CNC homology 1 (Bach1)." (PMID 27999449, 2016). "Therefore, BACH1 may be a significant target for effective therapeutic intervention in tumor metastasis development." (PMID 28000777, 2016). "Therefore, a reduction in the Bach1 activity may lead to an enhancement in the tumor-resistant phenotype." (PMID 25050144, 2014). "In the present study, we observed BACH1 was highly expressed in PLK1 overexpressed cells and tumor samples." (PMID 41284701, 2025). "Our data revealed that SDCBP and BACH1 expression show a significant positive correlation in TNBC cells and TNBC patients tumor tissues." (PMID 40263598, 2025).
tumor (continued). "In particular, it should be noted that consideration of BACH1 expression levels, particularly in luminal B subtype tumors among Black and White women, using a larger patient dataset would provide a better understanding of whether BACH1 expression is dependent on race or tumor subtypes." (PMID 40710214, 2025). "This process can either relieve BACH1’s downregulation of SLC7A11, inhibit ferroptosis, promote tumor growth, or upregulate the expression of pro-migration targets and accelerate tumor metastasis." (PMID 39664391, 2024). "BACH1 regulates the degradation and deposition of the ECM, creating a favorable environment for tumor metastasis." (PMID 38321558, 2024). "Of interest, ZBTB20 triggers increased production of IFN-α in MCL cells upon BACH1 silencing, indicating that ZBTB20 is very likely to participate in the BACH1-mediated regulation of the tumor immune microenvironment." (PMID 38397429, 2024). "Two GRNs, albeit comprising a smaller number of tumor cells, showed high activity for the TCF7L2 regulon (along with KLF8, FOXK1, FOXP2, BACH1) (labeled TCF7L2+) and CTCF (along with MAFG and NR1H) (labeled CTCF+) respectively." (PMID 38645034, 2024). "Two GRNs, albeit comprising a smaller number of tumor cells, showed high activity for the TCF7L2 regulon (along with KLF8, FOXK1, FOXP2, and BACH1) (labeled TCF7L2+) and CTCF (along with MAFG and NR1H) (labeled CTCF+), respectively." (PMID 38968122, 2024). "In ovarian cancer, BACH1 recruits HMGA2 to the promoter region of Snail, thereby promoting the EMT and motility of tumor cells." (PMID 38321558, 2024). "Thus, BACH1 may provide a mechanism by which tumor cells evade oxidative stress-induced senescence." (PMID 38255314, 2024). "Immunohistochemical analyses of tumor sections from patients with KRAS-mutant NSCLC showed correlations between BACH1 and VEGFA and BACH1 and VEGFR2." (PMID 37651203, 2023). "Thus, BACH1 may exert different actions in normal compared to tumor cells." (PMID 38129407, 2023). "BACH1 expression correlates with angiogenesis gene and protein expression in human NSCLC tumors and increases tumor vascularity and the response to anti-VEGF therapy in xenograft tumors." (PMID 37651203, 2023). "As lactate is the most abundant carbon source in the tumor microenvironment, lactate consumption was monitored using stable TNBC cell lines depleted of BACH1." (PMID 35406740, 2022). "The expression of BACH1 in BRCA and HNSC tumor tissue is negatively related to the purity of the tumor, while BACH1 in LGG is positively related to that of the tumor." (PMID 35651942, 2022). "To confirm previous findings as well as to determine the role of BACH1 as a MAFF binding partner, we knocked down BACH1 and measured tumor cell growth." (PMID 34262028, 2021). "Taken together, these data demonstrate that MAFF is a positive regulator of tumor cell invasion and metastasis by activating IL11/STAT3 pathways when binding to BACH1, especially under hypoxic conditions." (PMID 34262028, 2021). "It has been shown that Bach1 can form a complex with MAFG and the DNA methyltransferase DNMT3B, which resulted in the repression of tumor suppressor genes." (PMID 34949193, 2021). "Six genes (DNAJB6, RB1, VIMP/SELENOS, STEAP3, BACH1, and ALOX12) had a consistent mRNA expression level in tumor samples and prognosis in the univariate Cox analysis." (PMID 34075060, 2021). "When BACH1 or both BACH1 and MAFF were inhibited, tumor cell invasion and tube formation of HUVEC cells were also significantly decreased." (PMID 34262028, 2021). "VEGFC can, thus, be added to a growing list of tumor and metastatic proteins, including CXCR4 and MMP1, all of which are transcriptionally regulated by BACH1." (PMID 32132179, 2020). "Secondly we examined the biological consequence of reduced let-7 expression in NETs and metastasis by western blot analyses and immunohistochemistry on paired FFPE tumor and metastases tissues for HMGA2, BACH1 and MMP1." (PMID 25546138, 2014).